MIR1912 (microRNA 1912)
Synonyms: hsa-mir-1912; MIRN1912; mir-1912
Gene: MicroRNA gene on chromosome X (114,651,544 to 114,651,623, forward strand). Ensembl gene ENSG00000222321.
Gene Ontology:
Biological process: miRNA-mediated post-transcriptional gene silencing
Cellular component: RISC complex
Homologues: Orthologues: chimpanzee MIR1912 (100% identical), pig MIR1912 (96% identical), dog MIR1912 (95% identical), guinea pig MIR1912 (92% identical), rat Mir1912 (86% identical).